ITGA9 (integrin subunit alpha 9)
Description:
Integrin alpha-9/beta-1 (ITGA9:ITGB1) is a receptor for VCAM1, cytotactin and osteopontin. It recognizes the sequence A-E-I-D-G-I-E-L in cytotactin. ITGA9:ITGB1 may play a crucial role in SVEP1/polydom-mediated myoblast cell adhesion (By similarity). Integrin ITGA9:ITGB1 represses PRKCA-mediated L-type voltage-gated channel Ca(2+) influx and ROCK-mediated calcium sensitivity in vascular smooth muscle cells via its interaction with SVEP1, thereby inhibiting vasocontraction.
Synonyms: RLC; ITGA4L; ALPHA-RLC
Tractability: Antibody: its Gene Ontology location is reachable by antibodies, with high confidence; UniProt predicts a signal peptide or a membrane-spanning region; the Human Protein Atlas places it where antibodies can reach.
Target class: Membrane receptor
Gene: Protein-coding gene on chromosome 3 (37,452,090 to 37,823,507, forward strand). Ensembl gene ENSG00000144668.
Subcellular location: Membrane
Subcellular location (Human Protein Atlas): Vesicles; Cell Junctions; Nucleoplasm; Plasma membrane
Pathways (Reactome):
Extracellular matrix organization: ECM proteoglycans; Integrin cell surface interactions
Developmental Biology: Signal transduction by L1
Gene Ontology:
Molecular function: protein binding; integrin binding involved in cell-matrix adhesion; signaling receptor activity
Biological process: cell adhesion; negative regulation of vasoconstriction; osteoclast differentiation; cell-cell adhesion; cell-matrix adhesion; integrin-mediated signaling pathway
Cellular component: integrin alpha9-beta1 complex; cell surface; integrin complex; plasma membrane; basal plasma membrane; membrane
Genetic constraint (gnomAD): Loss-of-function variants: 47 observed, 107.92 expected, observed/expected ratio (o/e) 0.44, 90% interval 0.34 to 0.56. The upper end of that interval is the gene's LOEUF score, 0.56, which puts it in group 2 of 6, group 1 being the genes least tolerant of losing a copy. Missense variants: 1,166 observed, 1,308.6 expected, observed/expected ratio (o/e) 0.89, 90% interval 0.85 to 0.94. Synonymous variants: 501 observed, 496.39 expected, observed/expected ratio (o/e) 1.01, 90% interval 0.94 to 1.09.
Homologues: Orthologues: chimpanzee ITGA9 (99% identical), macaque ITGA9 (96% identical), dog ITGA9 (94% identical), pig ITGA9 (94% identical), rat Itga9 (90% identical), mouse Itga9 (90% identical), guinea pig ITGA9 (87% identical), tropical clawed frog itga9 (74% identical), zebrafish itga9 (65% identical), Drosophila melanogaster if (23% identical), Caenorhabditis elegans pat-2 (22% identical), Drosophila melanogaster ItgaPS5 (19% identical), and 2 more. Paralogues in human: ITGA4 (41% identical), ITGA1 (24% identical), ITGA8 (24% identical), ITGAD (24% identical), ITGA11 (24% identical), ITGA5 (24% identical), ITGAM (24% identical), ITGA7 (24% identical), ITGAX (24% identical), ITGAV (23% identical), ITGA2 (23% identical), ITGA10 (23% identical), and 5 more.
Diseases named in the same sentence as ITGA9 in open-access papers:
ITGA9 is named in the same sentence as 78 diseases in open-access papers, as found by Europe PMC text mining. Sharing a sentence is not in itself a finding about the gene and the disease. The quoted sentences say what the papers report.
breast cancer (9 papers, 2014 to 2023). A primary or metastatic malignant neoplasm involving the breast. "In contrast, ITGA9 deletion allele carriers were observed once in cases and once in controls, leaving its potential role in breast cancer predisposition uncertain." (PMID 25466287, 2014). "DCLRE1C operates in the DNA double-strand break repair pathway, defect of which has been strongly associated with breast cancer predisposition, and ITGA9 encodes α-integrin, which participates in the control of cell division, differentiation and migration." (PMID 25466287, 2014). "In addition, ITGA9 has been found to have a strong association with patient outcomes across a variety of tumor types including breast cancer." (PMID 37469704, 2023). "Here we have defined the exact breakpoints of six previously identified deletion alleles disrupting the CYP2C19, CDH19, CASP3, DCLRE1C, DAB2IP and ITGA9 genes, respectively, and evaluated their association with breast cancer risk and disease subtype using a Northern Finnish case–control cohort." (PMID 25466287, 2014). "ITGA9 has been related to high tumour grade, presence of distant metastases, and reduced overall survival in breast cancer patients." (PMID 36221013, 2022). "In this case, since it has been previously suggested that ITGA9 played a role in breast cancer (BC) progression, BC cell lines were also included to test the possibility of the compound in this neoplasia." (PMID 36221013, 2022). "Hypermethylation of CpG-island is considered to be the critical mediation mechanism of ITGA9 inactivation of breast malignant tumors." (PMID 33790909, 2021). "In triple-negative breast cancer, the level of ITGA9 is drastically higher than in other subtypes of breast cancer, which is related to worse distant metastasis-free survival and recurrence-free survival rates." (PMID 33790909, 2021). "Depletion of ITGA9 suppressed breast cancer progression and metastasis through GSK3/β-catenin pathway." (PMID 34350460, 2021). "In another study hypermethylation of ITGA9 at its first intron has been reported to be the major mechanism for its downregulation in breast cancer." (PMID 26372814, 2015). "The chromosomal region harboring ITGA9 has been reported to be deleted in several epithelial malignancies, including breast carcinoma." (PMID 25466287, 2014). "Furthermore, bioinformatics analysis on ITGA9 shows that its expression is significantly higher in TNBC than the other breast cancer sub-type." (PMID 37469704, 2023). "ITGA9 was significantly associated with OS and DSS respectively in AML, B cell lymphoma, lung cancer, colorectal cancer and esophagus cancer and colorectal cancer, breast cancer." (PMID 32581652, 2020). "Compared with ND, the transcript levels of ITGA9 indicated significant low expression in bladder cancer, brain and central nervous system cancer, breast cancer, leukemia, liver cancer, lung cancer and etc., suggesting that the down-regulation of ITGA9 was common in various types of cancer." (PMID 32581652, 2020). "Furthermore, studies have suggested that ITGA9 had the abnormal expression in numerous cancers and has been found to be crucial for a number of biological processes in many types of cancers, such as breast carcinoma, melanoma and lung cancer." (PMID 32581652, 2020). "In this study, we have identified high frequencies of cancer specific abnormal hypermethylation of the parts of promoter regions of integrin ITGA1, ITGA4, ITGA9, and nidogen NID1, NID2 genes in breast cancer." (PMID 33500458, 2021).
melanoma (8 papers, 2018 to 2025). A malignant, usually aggressive tumor composed of atypical, neoplastic melanocytes. "It targets ITGA9 to inhibit glucose metabolism, lactic acid production, proliferation and migration of melanoma cells while inducing cell apoptosis." (PMID 33790909, 2021). "This field of research provides a new direction for the treatment of melanoma with micro-RNA and lncRNA that target ITGA9 either directly or indirectly." (PMID 33790909, 2021). "ITGA9 is also highly expressed in melanoma tissues and promotes the proliferation and invasion of melanoma cells." (PMID 33335550, 2020). "Therefore, proliferation, apoptosis, metastasis of melanoma cells may be modulated via regulation of ITGA9-related non-coding RNAs." (PMID 34660316, 2021). "In addition, the long noncoding RNA (lncRNA) CCAT1 acts as a competing endogenous RNA that sponges miR-296-3p to up-regulate ITGA9 in vivo; thus, CCAT1 silencing inhibits melanoma cell growth." (PMID 33790909, 2021).
lung carcinoma (5 papers, 2014 to 2021). "The decreased expression of ITGA9 in lung cancer indicated potential genetic and epigenetic regulation mechanism." (PMID 34350460, 2021). "For example, multiple genes in the AT1 cell program were closely related to pulmonary veno-occlusive disease (PVOD) (Bmpr2 and Eif2ak4), lung cancer (Itga9 and Braf), pulmonary fibrosis (Cadm1 and Itgb6), pulmonary hypertension (Bmpr2 and Cav1), and pulmonary emphysema (Itgb6)." (PMID 34873160, 2021).
Chylothorax (3 papers, 2012 to 2023). The presence of chyle in the thoracic cavity. "Mutations in integrin-α9 (ITGA9) were identified in human fetuses with congenital chylothorax." (PMID 29125824, 2017). "Itga9−/− mice recapitulated this phenotype and died soon after birth with chylothorax." (PMID 29125824, 2017).
glioblastoma (3 papers, 2021 to 2025). The most malignant astrocytic tumor (WHO grade IV). "In the case of glioma, ITGA9 expression correlated with disease grade: normal tissue showed no expression of ITGA9 in astrocytes, oligodendrocytes or neurons, whereas glioblastoma multiforme and giant-cell glioblastoma showed high expression of this protein." (PMID 36221013, 2022).
hepatocellular carcinoma (3 papers, 2015 to 2025). A malignant tumor that arises from hepatocytes. "The research reviewed above reveals that ITGA9 has the potential to become a diagnostic biomarker for hepatocellular carcinoma, provides a potential treatment solution and, more importantly, shows notable tumour heterogeneity in different cancer types." (PMID 33790909, 2021). "Hypermethylation of ITGA9 was found in tumor samples from breast, kidney, cervix, ovary, lung, prostate, colorectal cancer, hepatocellular carcinoma and premalignant cervical lesions." (PMID 26372814, 2015).
non-small cell lung carcinoma (3 papers, 2015 to 2018). A group of at least three distinct histological types of lung cancer, including non-small cell squamous cell carcinoma, adenocarcinoma, and large cell carcinoma. "Downregulation of ITGA9 has been reported in human papilloma virus associated head and neck squamous cell carcinoma, non-small cell lung cancer (NSCLC), leukoplakia, lichen planus, and oral squamous cell carcinoma." (PMID 26372814, 2015). "However, ITGA9 has been previously reported to be downregulated in human squamous cell carcinoma of the head and neck, non-small-cell lung cancer, and oral squamous cell carcinoma." (PMID 29951557, 2018).
Arthritis (2 papers, 2020 to 2022). Inflammation of a joint. "The results are promising because it was already shown that blocking ITGA9 has beneficial effects in mouse models of experimental autoimmune encephalomyelitis and arthritis." (PMID 36618360, 2022). "It was already shown that blocking ITGA9 has beneficial effects in mouse models of arthritis and experimental autoimmune encephalomyelitis." (PMID 33185818, 2020).
atherosclerosis (2 papers, 2022 to 2023). A disease characterized by the build-up of fatty material and calcium deposition in the arterial wall resulting in partial or complete occlusion of the arterial lumen. "Each gene was expressed in both cell types with SVEP1 and ITGA4 more highly expressed in VSMCs and ITGA9 expression higher in endothelial cells, in keeping with the previous atherosclerosis studies." (PMID 35802072, 2022). "Mice lacking Itga9 in monocytes and smooth muscle cells also fail to phenocopy the atherosclerosis phenotype of mice lacking Svep157." (PMID 36792666, 2023).
bladder cancer (2 papers, 2018 to 2020). "Besides, ITGA9 mRNA level was significantly downregulated in bladder cancer tissues compared with the corresponding adjacent to the tumor tissues." (PMID 29951557, 2018).
colon cancer (2 papers, 2021 to 2024). "Simultaneously, ITGA9 is obviously up-regulated in already-developed drug-resistant colon cancer cells, whereas α9 is reported to be a promising target candidate for overcoming methotrexate resistance in colon cancer." (PMID 33790909, 2021). "ACTN1 may positively interact with ITGA9 to promote proliferation, invasion, and EMT in colon cancer." (PMID 39228892, 2024).
colorectal cancer (2 papers, 2015 to 2020). A primary or metastatic malignant neoplasm that affects the colon or rectum. "Genetic variation and epigenetic modification of ITGA9 are related with the tumorgenicity and progression of colorectal cancer." (PMID 32581652, 2020).
fetal hydrops (2 papers, 2012 to 2023). "Although the FC-r case had no ITGA9 mutation, it was included due to similar severity of FC and fetal hydrops." (PMID 22529953, 2012).
injury (2 papers, 2020 to 2022). Damage inflicted on the body as the direct or indirect result of an external force, with or without disruption of structural continuity. "Based on the available literature and our results, we suggest that XCL1 deserves further study, especially because XCR1 and ITGA9 seem to be important novel targets with beneficial properties for pharmacological intervention after brain injury." (PMID 33185818, 2020). "Moreover, both XCL1 receptors (XCR1 and ITGA9), seem to be important novel targets with beneficial properties for pharmacological intervention after nerve injury." (PMID 36618360, 2022).
leiomyoma (2 papers, 2022 to 2023). A well-circumscribed benign smooth muscle neoplasm characterized by the presence of spindle cells with cigar-shaped nuclei, interlacing fascicles, and a whorled pattern. "The feature selection resulted in a final model that consisted only of 19 genes, out of which only three, COL4A5, MFAP5, and ITGA9, were overexpressed in leiomyoma, while the rest were overexpressed in leiomyosarcoma)." (PMID 35216305, 2022).
leukemia (2 papers, 2012 to 2020). A malignant (clonal) hematologic disorder, involving hematopoietic stem cells and characterized by the presence of primitive or atypical myeloid or lymphoid cells in the bone marrow and the blood. "Taken together, the results demonstrated that ITGB4, ITGA6, ITGA9, and VE-cadherin are the candidate integrin genes with increased adhesion ability in EVI1high leukemia cells." (PMID 22295105, 2012).
liver cancer (2 papers, 2020 to 2021). An epithelial or non-epithelial malignant neoplasm that arises from the liver. "A previous study reported that silencing ITGA9 expression inhibits liver cancer growth and metastasis in vivo." (PMID 34222028, 2021).
lymphedema (2 papers, 2012 to 2023). Excess fluid collection in tissues, causing swelling. "Genetic predisposition of lymphatic dysfunction results in primary lymphedema such as genes pertaining to lymphagiogenesis (VEGFR3, FOXC2, SOX18, ITGA9 and etc.)are the influencing factor of primary lymphedema in defective form." (PMID 37986071, 2023). "Only a few hereditary lymphedema-associated gene loci, e.g. VEGFR3, ITGA9 and PTPN11, were detected in human fetuses with this condition; these cases had a poorer prognosis, due to defective lymphangiogenesis." (PMID 22529953, 2012).
rhabdomyosarcoma (2 papers, 2021 to 2022). A rare aggressive malignant mesenchymal neoplasm arising from skeletal muscle. "We have now deciphered the importance of ITGA9 in metastasis and provide evidence demonstrating its essentiality for metastatic dissemination in rhabdomyosarcoma and neuroblastoma." (PMID 36221013, 2022). "The previous results from our laboratory showed ITGA9 as a Notch pathway target and as an interesting player in the metastatic potential of rhabdomyosarcoma cells, whose inhibition by miR-7 and miR-234-5p exerted strong anti-oncogenic effects." (PMID 36221013, 2022). "This raises the possibility of using ITGA9-mediating miRNA as a novel therapeutic tool to avoid rhabdomyosarcoma progression." (PMID 33790909, 2021). "Herein, we describe the anti-metastatic effects of the genetic inhibition of ITGA9 in two different cancers: rhabdomyosarcoma (RMS), the most prevalent soft tissue sarcoma in children, and neuroblastoma (NB), the most common extracranial solid tumour in children." (PMID 36221013, 2022).
rheumatoid arthritis (2 papers, 2020 to 2023). A chronic, systemic autoimmune disorder characterized by inflammation in the synovial membranes and articular surfaces. "ITGA9 plays a role in inflammation as well as the autoimmune diseases rheumatoid arthritis and autoimmune encephalomyelitis in animal models." (PMID 37057071, 2023).
small cell lung carcinoma (2 papers, 2015 to 2018). Small cell lung cancer (SCLC) is a highly aggressive malignant neoplasm, accounting for 10-15% of lung cancer cases, characterized byrapid growth, and early metastasis. "It has been reported that ITGA9 plays supportive roles in breast and small-cell lung cancer." (PMID 29951557, 2018).
breast tumors (1 paper, 2021). "In breast tumors, ITGA9 expression was downregulated or totally absent in 44% of cases and intact or upregulated in 45% of cases." (PMID 33500458, 2021).
cardiac hypertrophy (1 paper, 2025). "Both Itga9 and Nppa have been linked to changes in blood pressure, while deletion of Enah and downregulation of Egf receptor result in cardiac hypertrophy and contractile dysfunction in mice." (PMID 40624174, 2025).
cervical squamous cell carcinoma (1 paper, 2020). A squamous cell carcinoma arising from the cervical epithelium. "For example, sequencing analysis also found that ITGA9 was significantly down-regulated in cervical squamous cell carcinoma." (PMID 32581652, 2020).
colon adenocarcinoma (1 paper, 2024). "ITGA9 is expressed in colonic glandular epithelial cells at the fetal stage and in colon adenocarcinoma, but not in normal adults." (PMID 39228892, 2024).
diabetic nephropathy (1 paper, 2025). "Recent studies have also found that miR-194-5p may participate in the progression of diabetic nephropathy by targeting ITGA9 to regulate macrophage migration and adhesion, thereby blocking the high glucose–induced upregulation of ITGA9 protein levels." (PMID 41334450, 2025).
dilated cardiomyopathy (1 paper, 2018). Cardiomyopathy which is characterized by dilation and contractile dysfunction of the left and right ventricles. "KEGG pathway analysis on cardiac loop genes reveals enrichments for terms, such as dilated cardiomyopathy, vasopressin-regulated water reabsorption, and hypertrophic cardiomyopathy (the genes within these terms include: Adcy6, Aqp3, Creb3l4, Des, Itgb5, Itga9, Myl2, Myl3, and Stx4a)." (PMID 30697540, 2018).
Down syndrome (1 paper, 2017). "Moreover, we found differentially methylated probes within ITGA9 and ADAM12 genes, whose methylation is altered in systemic sclerosis, and within the PRDM8 gene, whose methylation is affected in dyskeratosis congenita and Down syndrome." (PMID 28861129, 2017).
familial cancer (1 paper, 2009). "Insertions in integrin alpha 9 (ITGA9), located in a region of frequent homozygous deletions in tumor samples, and ADP-ribosylation factor-like 11 (ARL11), a genetic variant of which predisposes to familial cancer, were detected in the early phase, but never among the late phase samples." (PMID 19148292, 2009).
Granuloma (1 paper, 2020). A compact, organized collection of mature mononuclear phagocytes, which may be but is not necessarily accompanied by accessory features such as necrosis. "Only six genes (ADAMTS1, HSPB6, NR4A1, CXCL2, NPR1, ITGA9) were exclusively dysregulated in both lung and lymph node in sarcoidosis granulomas but not in CM or TB." (PMID 33276795, 2020).
Hypertension (1 paper, 2021). The presence of chronic increased pressure in the systemic arterial system. "A previous study found that a different SNP of ITGA9 is associated with hypertension (rs7640747, p = 4.8 × 10−7), consistent with our prediction." (PMID 33860000, 2021).
Lynch syndrome (1 paper, 2020). An autosomal dominant hereditary neoplastic syndrome characterized by the development of colorectal carcinoma and a high risk of developing endometrial carcinoma, gastric carcinoma, ovarian carcinoma, renal pelvis carcinoma, and small intestinal carcinoma. "In another study conducted on a Lynch syndrome family, it was found that the MLH1.ITGA9 fusion allele caused loss of heterozygosity (LOH) in five genes, including LRRFIP2, which resulted in the loss of mismatch repair capabilities." (PMID 32828126, 2020).